MMP9 (matrix metallopeptidase 9)
Diseases named in the same sentence as MMP9 in open-access papers (continued):
Sharing a sentence is not in itself a finding about the gene and the disease.
tumor (continued). "As the downstream effectors of p-ERK, MMP2 and MMP9 are important for tumor invasion and metastasis by degrading basement membrane components, while cyclinD1 acts on G1-S progression of the cell cycle, thus they may decipher the function of CASZ1 in HCC proliferation and metastasis." (PMID 29506567, 2018). "Specific MMP-9 inhibitors, such as GS-5745 (Andecaliximab), are being tested in clinical trials in combination with chemotherapy or immune checkpoint inhibitors in order to block paracrine signaling and metastasis and to alter the immune microenvironment within the tumor." (PMID 30558648, 2018). "MMP-9 has also been reported to be highly expressed in the malignant mesothelium; specifically its expression was found to be stronger in mesothelial cells closer to the metastatic tumor and in mesothelial cells with a stratified and inflamed appearance, than those remote from the tumor." (PMID 29393911, 2018). "Therefore, the patient’s prognosis differs depending on the specific state of the individual patient and whether MMP-9 expression occurs in the tumour or stromal cells." (PMID 30142200, 2018). "Thus, measuring salivary MMP-9 levels cannot be recommended in the routine diagnostic assessment for tumour recurrence during follow-up." (PMID 28160595, 2017). "In addition, several studies have suggested that MMP-9 is highly involved in the maintenance of CSC properties inside the tumour microenvironment, and changes in MMP-9 expression may affect the invasion property of CSC." (PMID 28606135, 2017). "Also, it has been proven as a regulator of MMP-9 to promote tumor invasion and metastasis." (PMID 28288190, 2017). "In addition, MMP3 protein levels are positively correlated with MMP9 activity in tumor tissues." (PMID 29137230, 2017). "The NGAL/MMP-9 complex may be useful in the assessment of tumor stage before surgical treatment." (PMID 29089666, 2017). "Some authors have not found an association of MMP-9 expression and tumour invasiveness." (PMID 28194042, 2017). "Results of our studies indicated that silencing of TGF-β1 in tumor cells in situ exerted a significant effect on tumor fibroblast proliferation, differentiation and expression of protumorigenic growth factors, in particular, MMP9, as well as myofibroblast differentiation." (PMID 28819116, 2017). "To uncover the potential molecular pathways underlying ANXA13-enhanced tumor cell invasion and migration, we determined whether the ANXA13 downstream protein MMP-9, which is known for its role in cancer metastasis and tumor cell migration and invasion, is involved in the process." (PMID 28423508, 2017). "Moreover, YKL-40 was likely to promote tumor angiogenesis by interacting with syndecan-1 on endothelial cells as well as metastasis by stimulating production of pro-inflammatory and pro-invasive factors such as MMP-9, CCL2 and CXCL2." (PMID 28036271, 2017). "Notably, miRNA-199a could trigger tumor progression through inhibiting functions of MMP9, a protein that could degrade the extracellular matrix." (PMID 28881744, 2017). "Therefore, we determined the expression of MMP-2 and MMP-9 in tumor sections." (PMID 26517521, 2016). "It has been shown that TβRI-ICD associates with p300 and activates genes involved with tumour invasion, such as MMP2; here, we show by knockdown of APPL proteins that the nuclear TβRI-ICD-APPL protein complex regulates MMP2 and MMP9 expression, which could promote cancer cell invasion." (PMID 26583432, 2016). "Besides, we also found that treatment with nifuroxazide could inhibit the expression of MMP-2, MMP-9 and p-Stat3 in A375 tumor tissues." (PMID 26830149, 2016).
tumor (continued). "Moreover, the meta-analysis revealed that overexpression of MMP-9 in tissue but not in serum was a risk factor of advanced T category, tumor stage and poor outcome." (PMID 26918342, 2016). "In addition, we performed IHC to determine whether knockdown of XIST can reduce the expression of Ki-67 and mmp-9 in tissues taken from tumor growth assay in nude mice." (PMID 27620004, 2016). "Baseline tumor biopsies in our study, which were sampled from the endoluminal surface of the deeply invasive tumors, would probably not have enabled a reliable estimation of whole tumor MMP9 expression for direct comparison with the patients’ circulating MMP9 levels." (PMID 27461255, 2016). "Activated macrophages are essential for tumor invasion via production of several matrix-metalloproteases (MMPs) such as MMP-9, which could destroy basement membrane and degrade the extracellular matrix (ECM), and thereby create a microenvironment conductive to tumor progression." (PMID 27793010, 2016). "Invasion of these structures may induce MMP9 expression in nearby tumor stromal cells." (PMID 27255663, 2016). "Moreover, because MMP-9 was most frequently assessed in tumor specimens, we also performed a systematic review of published research to clarify the prognostic significance of MMP-9 in tissue and serum, and other clinicopathological features were also examined in this study." (PMID 26918342, 2016). "In addition, mixed phenotypes of TAMs that co-express proinflammatory genes such as TNF and IL-1 together with known tumor-promoting genes including VEGFA and MMP9 have been observed in various tumor models including renal cell carcinoma and mammary adenocarcinoma." (PMID 27487154, 2016). "Moreover, MMP-9 expression positively correlated with PTK7 expression in ESCC tumor tissue." (PMID 27689325, 2016). "TANs within the primary tumor are protumoral, as they secrete the proangiogenic factor Bv8, which is also responsible for myeloid cells recruitment, especially at early stages of malignancy, as well as the proangiogenic matrix metalloproteinase MMP-9, both in larger amounts than their cognate TAMs." (PMID 26997761, 2016). "As our in vitro studies revealed expression changes of mesenchymal proteins, SNAIL and vimentin, and of MMP-2 and MMP-9 on cancer cells treated with the combination of metformin and selumetinib, we also investigated whether the combination therapy blocks tumour metastatic behavior in vivo." (PMID 26673006, 2016). "Furthermore, N-cadherin–affected tumor progression might be via enhanced MMP-9 signaling in a cross-talk regulatory mechanism." (PMID 27737648, 2016). "MMP-7 and MMP-9, which belongs to a family of zinc-dependent endopeptidases, are collectively capable of degrading essentially all of the components of the extracellular matrix (ECM), and are considered to be associated with invasion and migration of tumor cell." (PMID 26909600, 2016). "Thus, our model can help for checking the aggressive tumor invasion by blocking of uPA and MMP9." (PMID 26906973, 2016). "While ACPPD-Gd is relatively selective for MMP-2 and MMP-9, it is a generic contrast agent to any tissue that overexpresses those MMPs, particularly cancer, since MMPs are abundantly expressed in virtually all tumor lines during various stages of malignant progression and metastases." (PMID 26336058, 2015). "Finally, it is difficult to analyze survival outcome according to tumor MMP-9 expression." (PMID 25888323, 2015). "In addition, the involvement of Matrix metalloproteinase-9 (MMP9) in tumor invasion was examined." (PMID 26700636, 2015). "Moreover, K1 appears to be involved in endothelial cell immortalization and its expression in epithelial and endothelial cells results in the production of vascular endothelial growth factor (VEGF) and matrix metalloproteinase MMP-9, which can favor tumor angiogenesis and tumor cell growth in vivo." (PMID 25592960, 2015).
tumor (continued). "MMP9 promotes metastasis by facilitating tumor cell migration and invasion via cleavage of BM and other ECM components, and it has also been implicated in primary tumor growth by virtue of its position as both a downstream target and an upstream regulator of key oncogenic signaling pathways." (PMID 25961845, 2015). "In addition, morphine prevented IL-4-induced increase in MMP-9 production, indicating that opioids may prevent IL-4-expressing Th2 lymphocytes from promoting macrophage activation in the tumour microenvironment." (PMID 26078009, 2015). "sNEDD4 may regulate Mcl-1 and MMP9 to augment tumor invasion in a subgroup of patients." (PMID 25823820, 2015). "In addition to matrix degradation, MMP-9 is also reported to be involved in various aspects of tumor development and progression, including cancer stem cell niche formation, angiogenesis, dissemination, growth at the metastatic site and evasion of immunological surveillance." (PMID 26429875, 2015). "Therefore, the downregulation of MMP-9 expression may be a useful strategy for tumor metastasis intervention." (PMID 25374279, 2015). "Thus, α3β1-dependent APA may reflect an adaptation that occurs in tumorigenic cells to promote MMP-9 expression, thereby driving tumor growth and progression." (PMID 25751421, 2015). "In addition, we found that positive MMP-9 expression was associated with larger tumor size, higher TNM staging, negative ER and PR in the BCYW." (PMID 26656588, 2015). "NGAL can promote MMP-9 activity by forming a complex with the protease (MMP-9/NGAL), and these complexes appear to be elevated in the tumor samples as well as urine samples from cancer patients, suggesting the formation of the MMP-9/NGAL complex may play a role in tumor progression." (PMID 26663949, 2015). "The exact mechanism by which 2-DG reduces MMP-9 activity is not clear, but it may be responsible for the reduction in tumor invasiveness and associated angiogenesis." (PMID 26135741, 2015). "The regulation of MMP-9 expression during tumor progression may involve diverse mechanisms." (PMID 26229955, 2015). "Among the MMPs, MMP-9 is thought to play a pivotal role in the degradation of basement membrane collagen IV and therefore may mainly contribute to the invasive ability of various types of tumor cells." (PMID 26608825, 2015). "Additionally, tumor-cell-derived TNF-α directly accelerates MMP-9 expression in fibroblasts." (PMID 25767513, 2015). "In addition, MMP-9 has been shown to inhibit apoptosis of tumor cells in the lung." (PMID 26819959, 2015). "Thus, MMP-9 may be not only involved in vascular and neoplastic disease progression through the ECM degradation, but it can also contribute to define MSC fate, regulating the differentiation and survival program." (PMID 26090364, 2015). "However, if a cut-off value of 20% was applied, tumor MMP-9 positivity would be reduced to 27.3%." (PMID 25888323, 2015). "In tumor hypoxic microenvironment, tumor cells, tumor associated macrophages, dendritic cells, myeloid derived suppressor cells, and neutrophil cells secrete a variety of proangiogenesis and prolymphangiogenesis factors (e.g., VEGF, VEGF-C, MMP-9, TGF-β, and COX-2)." (PMID 26161392, 2015). "An aminobisphosphonate zoledronic acid (zoledronate) reduces mobilization of MDSCs through suppressing bone marrow progenitor-derived and tumor-derived MMP-9 although one study reports that zoledronic acid impairs tumor-associated macrophage proliferation but not MDSCs." (PMID 26078490, 2015). "Recent experiments documented that MMP9 might even exert tumor-suppressive properties." (PMID 25967040, 2015). "In addition, also note some MMP9 expression in the tumor cores, which may reflect differentiation of cells and is in agreement with the presence of GFAP." (PMID 26700636, 2015). "Also, intact HSPB1 was more detected on tumor endothelium of MMP9 null mice than wild type mice." (PMID 24465581, 2014).
tumor (continued). "If MMP-9 is playing a major role in the activation of Neu1 sialidase in complex with EGFR as our data suggest, logistically Snail in inducing MMP-9 in ovarian A2780 cancer cells may be the molecular mechanism(s) by which the Snail-MMP signaling axis functions in tumor neovascularization." (PMID 26932374, 2014). "In our study, HA enhanced both the pro-enzyme and active form of MMP-9 in GBC tumor cell supernatants as well as membrane-bound MMP-9 in membrane extracts (which may regulate pericellular ECM degradation from the tumor cell surface) in a CD44-dependent fashion in vitro." (PMID 24725816, 2014). "Interestingly, MMP-9 secreted by neutrophils or by other cells in the tumor stroma may prevent apoptosis of cancer cells." (PMID 24578639, 2014). "However, no statistical association was detected between MMP-9 expression and patients’ age (p = 0.664), tumor size (p = 0.056), histological grade (p = 0.088) or HER2 status (p = 0.064)." (PMID 24993803, 2014). "In addition, expression of MMP-2 and MMP-9 in tumor tissues was markedly enhanced by MVs." (PMID 24797571, 2014). "Besides, it was reported that BRG1 could promote MMP2 and MMP9 expression in some human tumor cells." (PMID 25304030, 2014). "This has been attributed to gelatinase B/MMP-9 induction of tolerogenic dendritic cells (tDC), through the release and activation of TGFβ, which increases the number of regulatory T (Treg) lymphocytes that promote tumour tolerance by suppressing CD8+ cytotoxic T cells." (PMID 24473089, 2014). "Gelatinase B/MMP-9 activates pro-inflammatory cytokines TNFα and IL-1β, increases the activity of chemokines CXCL1, CXCL4, CXCL7 and CXCL8, releases TGFβ from matrix stores, is released by activated neutrophils in TIMP-1-free form and acts as a nanomolar effector of tumour associated inflammation." (PMID 24473089, 2014). "This is the first report suggesting that the evaluation of active MMP-9 by immunohistochemistry and determination of its activation ratio by gelatin zymography may be a useful adjunct to the known clinicopathological factors in predicting tumor behavior." (PMID 24778099, 2014). "We investigated whether the mRNA expression of IL-6 in the control tumor xenografts had any correlation with the mRNA levels of invasion-associated genes such as CXCR4, MMP-2, and MMP-9 in response to systemic administration of paclitaxel and oral gavages of CYT387." (PMID 24782986, 2014). "In general, knockout technology has implicated MMP9 in skeletal growth plate vascularisation and in bone marrow derived CD11b+ myelomonocytic cell-mediated vasculogenesis in irradiated tumour tissues, with the absence of gelatinase B/MMP-9 associated with small tumours containing mature vessels." (PMID 24473089, 2014). "Neutrophil gelatinase B/MMP-9 regulates pericyte proliferation, apoptosis and recruitment during angiogenesis and mobilises the recruitment of bone marrow-derived angiogenic precursors to the tumour stroma enhancing the tumour angiogenic and vasculargenic process." (PMID 24473089, 2014). "In addition, MMP-9 can regulate the stability and permeability of newly formed tumor vessels." (PMID 24944618, 2014). "It has been proved MMP-9 could facilitate tumor progression, invasion, metastasis angiogenesis." (PMID 24992193, 2014). "Notably, MMP-2 and MMP-9 are important for tumor invasion and angiogenesis." (PMID 24520272, 2014). "Furthermore, when MMP-9 levels were evaluated in the cytoplasm of carcinoma cells present in 13 metastatic lymph nodes, it was found that all tumor cells (100%) displayed elevated levels of MMP-9 whereas the surrounding lymphocytic and stromal cells failed to express MMP-9." (PMID 25151367, 2014). "In addition, our findings highlight the role of tumour stroma in the biological behaviour of canine MMTs and suggest that uPA and MMP-9 may be potential targets for post-operative therapies." (PMID 23289974, 2013).
tumor (continued). "Thus, inhibition of MMP-9 expression could be a useful therapeutic modality to decrease the growth and invasive properties of tumor cells." (PMID 23407024, 2013). "Based on these hypotheses, we analyzed whether MMP-9 cleaves IL-2R α chains and which cell types produce MMP-9 in tumors, and we analyzed the relationships between levels of sIL-2R in sera and the number of tumor-associated macrophages." (PMID 24236041, 2013). "Moreover, tumor metastasis-related proteins, such as matrix metalloproteinase-9 (MMP-9) and urokinase plasminogen activator (u-PA), were decreased and the endogenous inhibitors tissue inhibitor of MMP-1 and plasminogen activator inhibitor-1 (PAI-1) were increased." (PMID 23690855, 2013). "In addition to induction of a migratory phenotype and directing metastasizing tumor cells to regional lymph nodes the CCR7/CCL21 axis may also foster tumor metastasis by preventing anoikis in cancer cells and up-regulation of matrix metalloproteinase-9 (MMP9)." (PMID 23667660, 2013). "Additionally MMP-9, through its extracellular remodeling activities, may facilitate the immigration of tumor cells into the pulmonary environment." (PMID 24399973, 2013). "Tumour buds may have a role in ECM degradation, a hypothesis supported by increased immunohistochemical expression of proteins such as matrix metalloproteinases MMP-2 and MMP-9, and urokinase plasminogen-activator receptor (uPAR) in high-grade tumour-budding cases." (PMID 22531633, 2012). "In addition, we speculate that CypA regulates the activity of MMP9, a key factor in tumor metastasis, although this should be investigated further in vivo, and the CypA-centered regulatory network should be elucidated in detail." (PMID 23031673, 2012). "Therefore, the MMP-9 expression may be closely related to proliferation, invasion and metastasis of tumour cells, and even to tumour angiogenesis." (PMID 23107277, 2012). "Therefore, inhibition of NF-κB may serve as an effective treatment strategy for many tumours through MMP-9 and VEGF downregulation and disruption of Akt signalling." (PMID 23039130, 2012). "Furthermore, both oncolytic viruses, parental GLV-1h68 and mmp-9-encoding GLV-1h255, significantly reduced the size of lumbar and renal lymph node metastases, indicating that MMP-9 enhances both virotherapy of the primary tumor and sustains the rVACV-metastasis reducing effect." (PMID 22917220, 2012). "In conclusion, this study showed that EMMPRIN played an important role in the invasion of SACC-LM cells through functionally mediating the expression of MMP-2 and MMP-9 both in tumor and stromal cells, and its antibody could effectively inhibit SACC-LM cells adhesion and invasion in vitro." (PMID 22200897, 2012). "High MMP-2 or MMP-9 expression in tumour or stromal cells might serve as prognostic predictors." (PMID 23107277, 2012). "Therefore, the inhibition of the Erk1/2 signaling pathways may result in reduced expression of MMP-9 and u-PA, as well as reduced tumor cell invasion." (PMID 22363545, 2012). "In particular, tumor cell-associated proteinases such as matrix metalloproteinases MMP2 and MMP9 might play a role in the decline of mechanical barriers represented by extracellular matrices and may be closely related to the incorporation process and importance of EPCs during tumor angiogenesis." (PMID 22496756, 2012). "Thus, we propose that LRP1 might regulate tumor migration and invasion by altering the level of MMP9." (PMID 22427881, 2012). "Thus, activation of AKT and ERK pathways-dependent MMP-9 expression may be widespread in tumor cells and contribute to tumor progression." (PMID 21738655, 2011). "Thus, MMP-9 from cells in the bone marrow transplant could restore tumour vasculature (determined by CD31 immunostaining and injection of Hoechst dye) and support tumour growth at a pre-irradiated site." (PMID 21587260, 2011). "However, other reports support the role of MMP-9 in tumor growth and angiogenesis." (PMID 22022379, 2011).